SMOC2 (SPARC related modular calcium binding 2)
Description:
Promotes matrix assembly and cell adhesiveness (By similarity). Can stimulate endothelial cell proliferation, migration, as well as angiogenesis.
Synonyms: SMAP2; MSTP117; DTDP1; DTDP1A; MST117; MSTP140; bA270C4A.1; bA37D8.1; dJ421D16.1
Tractability: Antibody: UniProt places it where antibodies can reach, with medium confidence; UniProt predicts a signal peptide or a membrane-spanning region; its Gene Ontology location is reachable by antibodies, with medium confidence.
Gene: Protein-coding gene on chromosome 6 (168,440,656 to 168,673,445, forward strand). Ensembl gene ENSG00000112562.
Subcellular location: Secreted, extracellular space, extracellular matrix, basement membrane
Gene Ontology:
Molecular function: protein binding; calcium ion binding; extracellular matrix binding; heparin binding
Biological process: positive regulation of angiogenesis; positive regulation of DNA biosynthetic process; positive regulation of endothelial cell chemotaxis; positive regulation of endothelial cell migration; positive regulation of fibroblast growth factor receptor signaling pathway; positive regulation of mitotic cell cycle; positive regulation of vascular endothelial growth factor signaling pathway; positive regulation of vascular wound healing; extracellular matrix organization
Cellular component: cell periphery; extracellular region; basement membrane; extracellular matrix
Genetic constraint (gnomAD): Loss-of-function variants: 34 observed, 54.93 expected, observed/expected ratio (o/e) 0.62, 90% interval 0.47 to 0.82. The upper end of that interval is the gene's LOEUF score, 0.82, which puts it in group 3 of 6, group 1 being the genes least tolerant of losing a copy. Missense variants: 544 observed, 568.48 expected, observed/expected ratio (o/e) 0.96, 90% interval 0.89 to 1.03. Synonymous variants: 242 observed, 230.76 expected, observed/expected ratio (o/e) 1.05, 90% interval 0.94 to 1.17.
Homologues: Orthologues: macaque SMOC2 (96% identical), rat Smoc2 (95% identical), mouse Smoc2 (95% identical), guinea pig SMOC2 (90% identical), dog SMOC2 (90% identical), pig SMOC2 (90% identical), chimpanzee SMOC2 (76% identical), zebrafish smoc2 (66% identical), Drosophila melanogaster magu (29% identical), Caenorhabditis elegans smoc-1 (14% identical). Paralogues in human: SMOC1 (53% identical).
Diseases named in the same sentence as SMOC2 in open-access papers:
SMOC2 is named in the same sentence as 98 diseases in open-access papers, as found by Europe PMC text mining. Sharing a sentence is not in itself a finding about the gene and the disease. The quoted sentences say what the papers report.
Brachycephaly (14 papers, 2010 to 2023). An abnormality of skull shape characterized by a decreased anterior-posterior diameter. "In the skeletal system, SMOC2 is involved in the development of bones; for example, mutations in the SMOC2 gene have been linked to canine brachycephaly, and SMOC2 deletion in zebrafish has been linked to craniofacial skeletal dysplasia." (PMID 36698376, 2023). "Examples of such variants include the brachycephaly associated SMOC2 and BMP3 variants and chondrodysplasia-associated FGF4 retrogenes on chromosomes 12 and 18, and there are likely more, yet undiscovered variants." (PMID 33599851, 2021). "It is highly likely, however, that the association between SMOC2 and brachycephaly came first, paving the way for the subsequent association of both with cesarean section rate." (PMID 31263560, 2019). "A few of these loci, such as CACNA2D3 and MSRB3, have been previously implicated in human reproductive pathologies, whereas others have been associated with domestication-related traits, including brachycephaly (SMOC2) and coat curl (KRT71)." (PMID 31263560, 2019). "For example, one of the variants that we found to be associated with cesarean section rate is in an intron of SMOC2, a gene previously associated with brachycephaly in dogs." (PMID 31263560, 2019). "The first significantly associated SNP is in the intron between exons 13 and 14 of SMOC2, a gene that is associated with dog brachycephaly and whose variation accounts for 36% of facial length variation in dogs." (PMID 31263560, 2019). "In order to evaluate the molecular contribution to brachycephalic skull shape, the DVL2 mutant breeds were genotyped for the previously identified brachycephaly associated Line insertion affecting SMOC 2 splicing." (PMID 30521570, 2018). "It is intriguing that numerous copy-number variants spanning SMOC2 are associated with human phenotypes, including brachycephaly, hydrocephalus, long face (vertical), and hypertelorism." (PMID 28552356, 2017). "Conceivably, a combination of variants promoting brachycephaly (e.g. Smoc2), on a background of those promoting growth (Igf-1) may place the Boxer at extreme risk of premature ageing and brain tumours." (PMID 31467332, 2019). "The results of these studies show association of brachycephaly with the RUNX2 gene on CFA12, SMOC2 on CFA1 and BMP3 on CFA32, chondrodysplasia with FGF4 retrogene on CFA12 and CFA18 and also with skull size." (PMID 36230363, 2022). "We distilled the CFA1 locus to reveal a haplotype overlapping with SMOC2 as the major contributor to brachycephaly." (PMID 28552356, 2017). "The second candidate gene for brachycephaly, SMOC2, was located just outside of the critical interval for brachycephalic head type." (PMID 20224736, 2010). "In canines with brachycephaly, SMOC2 is downregulated, due to alternative splicing caused by a LINE-1 insertion, which may indicate a role for SMOC2 in bicoronal (or brachycephalic) pediatric craniosynostosis." (PMID 36982425, 2023). "Analogously, a transposon insertion at the SMOC2 locus is associated with brachycephaly in most–but not all–dogs." (PMID 32433666, 2020). "Our data suggest that SMOC2 dysfunction is responsible for canine brachycephaly." (PMID 28552356, 2017).
endometrial cancer (9 papers, 2020 to 2024). Primary or metastatic malignant neoplasm involving the endometrium (mucous membrane that lines the endometrial cavity). "LE cells were correlated with SMOC2, encoding an extracellular glycoprotein recognized as an endometrial cancer stem cell signature." (PMID 35086476, 2022). "For instance, increased SMOC2 is associated with lymph node metastasis, distant metastasis, decreased chemosensitivity and a poor prognosis in endometrial cancer." (PMID 36513634, 2022). "Most recently, it was demonstrated that SMOC2 expression in endometrial carcinoma was closely associated with the cancer stem cell (CSC) markers, CE133 and CD44, and the silencing of SMOC2 enhanced chemosensitivity." (PMID 32184420, 2020). "In endometrial cancer, the SMOC2-related activation of WNT/β-catenin signalling promoted the progression of endometrial cancer since this pathway is vital for cell growth, differentiation, proliferation, and survival." (PMID 38539419, 2024). "A recent study identified SPARC-related modular calcium-binding 2 (SMOC–2) as a novel endometrial cancer stem cell signature gene and demonstrated that SMOC-2 is involved in activation of the Wnt/β-catenin pathway." (PMID 34068065, 2021). "Furthermore, SMOC2 silencing resulted in the diminished clonogenic potential of endometrial cancer and reduced the expression of stemness-related genes, including SOX2, OCT4, and NANOG." (PMID 38539419, 2024). "At the most recent, a study pointed that cancer stem cells are responsible for cancer proliferation and chemoresistance, it was found that SPARC-related modular calcium binding 2 (SMOC-2) drive the endometrial cancer chemoresistance functional as a endometrial cancer stem cell molecule." (PMID 33041661, 2020). "In endometrial cancer stem cells, WNT10B activity is regulated by the matricellular glycoprotein SPARC-related modular calcium binding 2 (SMOC-2)." (PMID 36814601, 2023).
colorectal cancer (6 papers, 2020 to 2024). A primary or metastatic malignant neoplasm that affects the colon or rectum. "A recently published study indicates that SMOC2 is an independent prognostic marker in patients with colorectal cancers." (PMID 36935650, 2022). "SMOC2 is also considered an intestinal stem cell signature gene and plays a key role in colorectal cancer cell motility, proliferation and liver metastasis." (PMID 36513634, 2022). "The involvement of the integrin pathway in SMOC2 signaling was also confirmed in the SMOC2 induction of metastasis using a colorectal cancer model." (PMID 35869056, 2022). "We aimed to investigate the expression profile of SPARC-related modular calcium-binding protein 2 (SMOC2) during colorectal cancer (CRC) progression and assess its prognostic impact in CRC patients." (PMID 32884102, 2020). "In colorectal cancer, ARNTL2 is identified as a potential biomarker for tumor invasiveness and aggressiveness and ARNTL2 knockdown suppresses cell migration, invasion, and proliferation through inhibiting SMOC2-EMT expression and PI3K/AKT signaling pathway." (PMID 38956029, 2024).
heart failure (6 papers, 2022 to 2025). Inability of the heart to pump blood at an adequate rate to meet tissue metabolic requirements. "By intersecting the findings from all three algorithms, we pinpointed four diagnostic genes for the pre-decompensation stage of heart failure: SMOC2, OGN, FCN3, and SERPINA3." (PMID 39717447, 2024). "In conclusion, biomarkers such as FCN3 and SMOC2 exhibit potential for diagnosis, emphasizing the necessity of continued investigation into their roles as diagnostic tools and therapeutic targets in heart failure management." (PMID 40297163, 2025). "SMOC2 has been depicted as significantly associated with the pathophysiology of heart failure." (PMID 40297163, 2025). "Ultimately, a total of four genes (FCN3, FREM1, MNS1, and SMOC2) exhibited significant co-expression in individuals suffering from heart failure." (PMID 40297163, 2025). "Research indicates that SMOC2 expression escalates in rats experiencing heart failure, and silencing SMOC2 can mitigate heart failure symptoms by modulating autophagy via the TGF-β1/Smad3 signaling pathway." (PMID 39717447, 2024). "In addition, a network analysis of expression profile data has identified that SMOC2 may be implicated in the pathogenesis of heart failure, which may allude to a possible connection between SMOC2 and cardiac fibrosis despite the lack of studies demonstrating this link." (PMID 36935650, 2022). "Moreover, alterations in autophagy observed with SMOC2 knockdown demonstrate its influence on cellular stress responses in heart tissue, implying that SMOC2 can be a target for therapeutic strategies in heart failure management." (PMID 40297163, 2025). "Furthermore, in studies involving rat models of heart failure, knockdown of SMOC2 resulted in improved cardiac function and attenuation of collage deposition, showcasing its potential involvement in cardiac remodeling and fibrosis." (PMID 40297163, 2025). "In a study of humans with heart failure, a negative correlation was found between SMOC2 and monocytes." (PMID 38601075, 2024).
hepatocellular carcinoma (6 papers, 2020 to 2024). A malignant tumor that arises from hepatocytes. "In fact, SMOC2 has been shown to be important for metastasis in colon cancer, lung adenocarcinoma and endometrial carcinoma, and proliferation in hepatocellular carcinoma." (PMID 35869056, 2022). "In hepatocellular carcinoma cells, SMOC2 expression was shown to significantly reduce cell proliferation, migration, and invasion abilities." (PMID 32184420, 2020). "SMOC2 promotes proliferation and cell cycle progression in hepatocellular carcinoma cells." (PMID 36513634, 2022). "Since SMOC2 was found to promote the proliferation of hepatocellular carcinoma cells by enhancing FAK signaling, we wondered whether SMOC2 also enhances FAK signaling in MEFs." (PMID 36698376, 2023).
Oligodontia (6 papers, 2013 to 2023). The absence of six or more teeth from the normal series by a failure to develop. "The gene SMOC2 is related to dental problems in carriers of pathogenic homozygous variants, including oligodontia, microdontia and abnormally shaped teeth." (PMID 36935482, 2023). "Point mutations in SMOC2 were identified independently in patients with dentin dysplasia type I syndrome, whose hallmarks include severe oligodontia and microdontia." (PMID 28552356, 2017). "A novel RA-inhibited target is the matricellular protein Smoc2, whose mutation in human produces oligodontia, microdontia, abnormal root development, dentin dyplasia, and reduced alveolar bone growth." (PMID 28111553, 2016). "We report a patient with a loss-of-function of the secreted matricellular protein SMOC2 (SPARC related modular calcium binding 2) presenting severe oligodontia, microdontia, tooth root deficiencies, alveolar bone hypoplasia, and a range of skeletal malformations." (PMID 32908163, 2020). "Smoc2 is a small Ca-binding protein that has recently been implicated in oligodontia in humans." (PMID 23516636, 2013).
breast carcinoma (4 papers, 2019 to 2024). "For example knocking down SMOC2 in SKBR3 breast cancer cells greatly reduced the ability of the activated Ran mutant to stimulate anchorage-independent growth." (PMID 32184420, 2020). "Moreover, SCUBE2, TMEM26, and SMOC2 were validated as subtype-specific coding genes in luminal A breast cancer, CDK12 and SDC1 in HER2 breast cancer and PSAT1 in triple negative breast cancer in TCGA and GEO datasets." (PMID 31801944, 2019).
lung adenocarcinoma (4 papers, 2020 to 2022). A carcinoma that arises from the lung and is characterized by the presence of malignant glandular epithelial cells. "In lung adenocarcinoma, SMOC2 functions as a secreted prometastatic factor." (PMID 36513634, 2022). "Additionally, in 482N1 lung adenocarcinoma cells, SMOC2 knockdown suppressed clonal growth and metastatic seeding although it did not affect proliferation or cell death under standard culture conditions." (PMID 32184420, 2020). "In addition, SMOC2 knockdown in lung adenocarcinoma cells led to reduced clonal growth and metastatic seeding." (PMID 32884102, 2020).
Myocardial fibrosis (4 papers, 2022 to 2025). "In myocardial fibrosis, SMOC2 participates in regulating the proliferation and differentiation of cardiac fibroblasts through activation of the ILK/p38 signalling pathway." (PMID 40913254, 2025). "Meanwhile, a reduction in SMOC2 levels has the potential to mitigate myocardial fibrosis through the suppression of the ILK/p38 signaling pathway." (PMID 40297163, 2025). "To further clarify the role of SMOC2 in the proliferation and differentiation of CFs, we used western blotting to detect the expression levels of SMOC2 in mouse myocardial fibrosis tissues and hypoxic intervention in CFs after MI." (PMID 40913254, 2025). "Results showed that the expression level of SMOC2 gradually increased with prolonged ischaemia and hypoxia time in myocardial fibrosis tissues and hypoxic intervention in CFs after MI." (PMID 40913254, 2025). "In the present study, we found that SMOC2 knockdown effectively inhibited myocardial fibrosis in HF rats and alleviated myocardial injury, which was consistent with the previous studies." (PMID 37465345, 2023). "A study investigating the relationship between SMOC2 and myocardial fibrosis has yet to be conducted." (PMID 36935650, 2022). "Moreover, SMOC2 suppression has been shown to alleviate myocardial fibrosis via the ILK/p38 pathway." (PMID 40913254, 2025). "Our study confirmed that SMOC2 was upregulated in myocardial fibrosis post‐MI and in CFs treated under hypoxic conditions and that knockdown of SMOC2 could regulate the proliferation and differentiation of CFs." (PMID 40913254, 2025). "Given that the AKT and AMPK pathways have been implicated in the pathophysiology of fibrosis, we examined whether these pathways are involved in the process of SMOC2-medicated myocardial fibrosis." (PMID 36935650, 2022). "The role and mechanisms of SMOC2 in myocardial fibrosis were further examined and analyzed." (PMID 36935650, 2022). "However, our study on the role of SMOC2 in myocardial fibrosis is limited." (PMID 40913254, 2025). "Our study implied that the therapeutic silencing of SMOC2 can improve ISO-induced myocardial fibrosis and heart function reduction in vivo, and ameliorate proliferation and collagen deposition of CFs induced by TGFβ in vitro, and the down-regulation of ILK/p38 may be the underlying mechanism." (PMID 36935650, 2022).
pulmonary fibrosis (4 papers, 2022 to 2025). Chronic progressive interstitial lung disorder characterized by the replacement of the lung tissue by connective tissue, leading to progressive dyspnea, respiratory failure, or right heart failure. "Notably, SMOC2 deficiency was found to reduce bleomycin-induced pulmonary fibrosis by restraining TGF-β1/Smads pathway." (PMID 37465345, 2023). "In addition, SMOC2 also participates in pulmonary fibrosis and hepatic steatosis caused by a high-fat diet targeting TGFβ1 pathways." (PMID 36935650, 2022). "A subsequent study discovered that SMOC2 knockout was available to mitigate bleomycin-induced pulmonary fibrosis." (PMID 36935650, 2022). "Additionally, SMOC2 promotes pulmonary fibrosis and hepatic steatosis by modulating the TGF‐β/SMAD, AKT and ERK signalling pathways." (PMID 40913254, 2025). "Moreover, it has been reported that SMOC2 silencing can suppress pulmonary fibrosis and kidney fibrosis." (PMID 37465345, 2023). "Secreted modular calcium-binding protein 2 (SMOC2), a factor expressed in almost all tissues, was found to inhibit lung fibrosis progression in SMOC2−/−." (PMID 36834561, 2023).
thyroid cancer (4 papers, 2020 to 2023). "Studies of liver cancer 34, colon cancer 35, and thyroid cancer 36 have shown that SMOC2 can regulate malignant tumor progression, can serve as a tumor stem cell marker, and is closely related to patient prognosis." (PMID 34976169, 2022). "Real time-PCR analysis with fresh-frozen tissues showed that SMOC2 mRNA expression in PTCs was substantially lower than the expression in matched non-cancerous thyroid tissues, consistent with the results from thyroid cancer cell lines." (PMID 32184420, 2020). "With the exception of the normal thyroid cell line, Nthy-ori 3–1, all thyroid cancer cell lines evaluated (three PTCs and two anaplastic carcinomas) exhibited negligible levels of SMOC2 expression." (PMID 32184420, 2020). "In thyroid cancer with BRAFV600E mutations, SMOC2 expression is reduced, which suggests that the use of BRAF inhibitors may promote the expression of SMOC2 and improve the prognosis of patients." (PMID 34923978, 2021). "Our findings of SMOC2 expression down-regulation in PTC and its association with improved clinical outcomes clearly suggest that SMOC2 likely acts as a tumor suppressor in thyroid cancers." (PMID 32184420, 2020). "As there has been no study on SMOC2 expression in thyroid cancers, here we aimed to investigate the expression profile of SMOC2 in various thyroid diseases including a large cohort of PTCs and to analyze the prognostic impact of SMOC2 as well as its correlation with clinicopathological features." (PMID 32184420, 2020).
Arthritis (3 papers, 2022 to 2023). Inflammation of a joint. "On the other hand, the endogenous secreted modular calcium-binding protein 2 (SMOC2) has been recently recognized as a key molecule to control the aggressive behavior in FLSs during arthritis." (PMID 36835620, 2023). "SMOC2 knockdown also decreased the severity of arthritis in CIA rats." (PMID 36513634, 2022). "Through direct and indirect binding to SOX4 TF, several upstream factors and signaling molecules have been recently reported to target SOX4 during arthritis, such as ROS)/TGF, TNF, SMOC2, AGEs, Lnc PART1, and the miRNA, miR-31." (PMID 36835620, 2023).